GSTZ1 (glutathione S-transferase zeta 1)
Diseases named in the same sentence as GSTZ1 in open-access papers (continued):
Sharing a sentence is not in itself a finding about the gene and the disease.
cancer (15 papers, 2016 to 2025). A tumor composed of atypical neoplastic, often pleomorphic cells that invade other tissues. "GSTZ1, a glutathione S-transferase, exhibits context-dependent functions across various cancers, closely associated with tissue-specific microenvironments." (PMID 41474538, 2025). "Consistently, the silence of METTL6 and LCMT1 decreased cancer cell migration, and depletion of GSTZ1 and ADH4 increased the cancer cell migration ability." (PMID 36341373, 2022). "GSTZ1 is an enzyme that participates in phenylalanine/tyrosine catabolism and is frequently deregulated in cancers; however, its role in tumorigenesis is largely unknown." (PMID 38398111, 2024). "GSTZ1 and GSTA1 have also been found to be associated with various forms of cancer." (PMID 36291099, 2022). "Since overexpression of GSTZ1 associated with downregulation of several glycolytic genes, we consider it possible that the suppression of tyrosine catabolism can be a mechanism by which HCC switch to aerobic glycolysis during cancer progression." (PMID 32542016, 2020). "Interestingly, DCA, a substrate and mechanism‐based inactivator of GSTZ1‐1, also reverses the Warburg effect in cancer cells and has been proposed for use in targeted therapy against cancer." (PMID 31267557, 2019). "In addition, GSTZ1 modulates sensitivity of cancer cells to dichloroacetate by controlling chloride concentrations." (PMID 27509054, 2016). "CPEB3, GHR, GSTZ1, and KLF8 were especially crucial molecules in the onset and progression of diseases and have been widely investigated in HCC or other forms of malignant tumors." (PMID 36827016, 2023). "In this study, in order to gain an in-depth understanding of the roles of HPGDS, GSTZ1, and GSTA1—the less-studied members of the GST family—in tumorigenesis and development, we first performed a pan-cancer bioinformatics analysis." (PMID 36291099, 2022). "Interestingly, while we found that GSTZ1 mRNA was significantly increased in GBM, we noticed that the protein level of GSTZ1 was significantly reduced in this cancer type, suggesting that there may be abnormalities in the translation, modification, or protein stability of GSTZ1 in GBM." (PMID 36291099, 2022). "Second, pan-cancer co-expression analysis for miRNA-target interaction in HCC using starBase showed that miR-539 level negatively correlated with TAT, HPD, GSTZ1 and FAH expression (r = -0.221, r = -0.193, r = -0.123, r = -0.166)." (PMID 32542016, 2020). "Considering the dual roles of NRF2 in cancer, the specific role of NRF2 activation in DEN/CCl4‐induced hepatocarcinogenesis requires further study using, for example, Gstz1 and Nrf2 double knockout mice and investigating its function in different stages of tumorigenesis." (PMID 31267557, 2019).
Genetic diseases (2 papers, 2019 to 2020). "Genetic diseases due to deficiencies of all enzymes in Phe/Tyr catabolic pathway have been well documented, with the exception of GSTZ1‐1." (PMID 31267557, 2019).
metabolic disorder (2 papers, 2018 to 2025). "MAAID is a rare metabolic disorder resulting from pathogenic variants in the GSTZ1 gene." (PMID 41009955, 2025).
peripheral neuropathy (2 papers, 2019 to 2025). A disorder affecting the peripheral nervous system. "DCA metabolism slows down with age, and DCA-induced GSTZ1 inactivation is 25 to 30 times higher in adults than in children, which increases the risk of peripheral neuropathy in adults." (PMID 40922281, 2025). "GSTZ1 genotypes in the protein coding and promoter regions, known to affect the rate and amount of enzyme activity were investigated in relation to DCA concentrations and peripheral neuropathy, the most common DCA associated toxicity." (PMID 31788319, 2019).
kidney disease (1 paper, 2024). "Accordingly, SDS–PAGE analysis of urine samples showed a massive increase in serum albumin (also known as albuminuria) in the animals treated with the vectors targeting Hgd and Gstz1 following NTBC removal, indicative of kidney disease." (PMID 39178380, 2024).
GSTZ1 also shares sentences with these, for which no sentence is quoted: liver dysfunction (2 papers); rectum adenocarcinoma (2); colon cancer (1); endometrial cancer (1); head and neck cancer (1); liver failure (1); lung adenocarcinoma (1); melanoma (1); metabolic dysfunction-associated steatotic liver disease (1); multiple myeloma (1); pancreatic cancer (1); prostate carcinoma (1); small cell lung carcinoma (1).